HTR5BP (5-hydroxytryptamine receptor 5B, pseudogene)
Synonyms: 5-HT5B; GPR134; HTR5B
Gene: Transcribed unprocessed pseudogene on chromosome 2 (117,859,427 to 117,903,338, forward strand). Ensembl gene ENSG00000125631.
Diseases named in the same sentence as HTR5BP in open-access papers:
HTR5BP is named in the same sentence as 7 diseases in open-access papers, as found by Europe PMC text mining. Sharing a sentence is not in itself a finding about the gene and the disease.
HTR5BP shares sentences with these, for which no sentence is quoted: Anxiety (4 papers); depression (2); cancer (1); memory (1); neuroblastoma (1); neurological disorders (1); psychiatric disorder (1).